RBFOX1 (RNA binding fox-1 homolog 1)
Diseases named in the same sentence as RBFOX1 in open-access papers (continued):
Sharing a sentence is not in itself a finding about the gene and the disease.
dilated cardiomyopathy (2 papers, 2018 to 2022). Cardiomyopathy which is characterized by dilation and contractile dysfunction of the left and right ventricles. "Rbfox1 also regulates splicing of a MEF2A exon in mouse and zebrafish heart that is mis-spliced in cells from human patients with dilated cardiomyopathy, and Rbfox1 and Rbfox2 cooperatively regulate splicing of Mef2D during C2C12 differentiation." (PMID 34996845, 2022). "Specifically, Rbfox1 expression in dilated cardiomyopathy (DCM) failing hearts was significantly lower than non-failing hearts." (PMID 28949795, 2018). "In human hearts, we found that the mRNA level of splicing factor Rbfox1, but not Rbfox2, was downregulated in dilated cardiomyopathy, and CACNA1C mRNA level was dramatically decreased in the both of dilated and ischemic cardiomyopathy." (PMID 28949795, 2018).
facioscapulohumeral muscular dystrophy (2 papers, 2013 to 2014). An autosomal dominant disorder affecting the skeletal muscles of the face, scapula, and upper arm. "A recent study indicated that the knockdown of Rbfox1 inhibits muscle differentiation, and that RBFOX1 expression was altered in a mouse model of facioscapulohumeral muscular dystrophy." (PMID 25211016, 2014).
fragile X syndrome (2 papers, 2017 to 2019). A genetic syndrome caused by mutations in the FMR1 gene which is responsible for the expression of the fragile X mental retardation 1 protein. "For this analysis, one subject with Fragile X syndrome was excluded but three subjects with clinically significant CNVs (A2BP1/RBFOX1 deletion (1.0 < WB5HT-z < 1.75), maternal interstitial duplication 15q11-q13 (Normal-5HT group), and NRXN3 deletion (Normal-5HT group)) were included." (PMID 28344757, 2017).
Huntington disease (2 papers, 2015 to 2026). Huntington disease (HD) is a rare neurodegenerative disorder of the central nervous system characterized by unwanted choreatic movements, behavioral and psychiatric disturbances and dementia. "G-4 genes included 6 genes: Btg3 associated nuclear protein (Banp), Ephx2, retinoid X receptor gamma (Rxrg), Ryr1, RNA-binding protein fox-1 homolog 1 (Rbfox1) and Zbtb16 categorized as ‘hereditary disorder (Huntington's disease)'." (PMID 26165378, 2015). "In the present study, we investigated gene expression profiles in the kidneys, and unexpectedly found that 6 SHRSP-specific genes isolated from the rats at 6 weeks of age (Banp, Ephx2, Rbfox1, Rxrg, Ryr1 and Zbtb16) were annotated to ‘Huntington's disease'." (PMID 26165378, 2015).
Insulin resistance (2 papers, 2020 to 2023). Increased resistance towards insulin, that is, diminished effectiveness of insulin in reducing blood glucose levels. "Two variants associated with the 15th percentile of z-insulin were located on genes previously linked with insulin secretion and beta cell function (RBFOX1) and measures of insulin resistance (SH3RF3)." (PMID 37420130, 2023).
lung carcinoma (2 papers, 2013 to 2022). "As well as refractive error, RBFOX1 polymorphisms are associated with blood pressure, allergy and lung cancer." (PMID 36395078, 2022). "Among the top genes in Hispanic-American population, RBFOX1 (RNA binding protein, fox-1 homolog, C. elegans, 1 [MIM 605104]) was reported to be related to survival in lung cancer patients." (PMID 23829686, 2013).
melanoma (2 papers, 2013 to 2023). A malignant, usually aggressive tumor composed of atypical, neoplastic melanocytes. "Interestingly, in a recent study the 5’ untranslated region of RBFOX1 was also rearranged in 4/25 melanoma, pointing to the possible importance of this part of the gene." (PMID 23286373, 2013).
metastatic tumor (2 papers, 2014 to 2025). "The results indicated that, compared to primary tumor tissues, the expression levels of PTBP3, RBFOX1, SRRM2, YBX3, and QKI were significantly higher in metastatic tumor tissues." (PMID 40270362, 2025).
alcohol use disorder (1 paper, 2020). "We have hence examined the association of four RBFOX1 single nucleotide polymorphisms, previously found related to aggressive traits, with aggressiveness, personality, and alcohol use disorder in birth cohort representative samples." (PMID 33329073, 2020). "Alcohol use is a most salient mediator to aggressiveness, so the association of RBFOX1 polymorphisms with lifetime prevalence of alcohol use disorder by age 25 was examined." (PMID 33329073, 2020). "Two out of four analyzed RBFOX1 variants, rs8062784 and rs12921846, were associated with the occurrence of alcohol use disorder." (PMID 33329073, 2020). "Two of the RBFOX1 variants were associated with alcohol use disorder, rs8062784 in males and rs12921846 in females." (PMID 33329073, 2020). "Thus, the findings that RBFOX1 variants appear to be associated with personality traits and alcohol use disorder merit attention in further studies." (PMID 33329073, 2020).
brain cancer (1 paper, 2022). A primary or metastatic malignant neoplasm affecting the brain. "However, RBFOX1 (rs8044700) near LMF1 in our TPMI study has an alternative splicing function to modify brain neoplasms and tend to be associated with malignancy." (PMID 35887658, 2022). "For the PPI network, primarily signals in the malignant brain neoplasm associated with DPP6, RBFOX1, LMF1, and EDARADD to present regulation of alternative splicing of RNA by APP6 and RBFOX1, maturation of specific proteins in ER by LMF1, and activation of NF-κB through EDARADD." (PMID 35887658, 2022).
complication (1 paper, 2024). Any disease or disorder that occurs during the course of, or because of, another disease, treatment, or procedure. "Therefore, targeting Rbfox1 to correct the aberrant splicing of the CaV1.2 channel in vascular smooth muscle may provide a promising approach for the management of diabetic vascular complications." (PMID 38575795, 2024).
conduct disorder (1 paper, 2025). A disorder diagnosed in childhood or adolescence age group characterized by aggressive behavior, deceitfulness, destruction of property or violation of rules that is persistent and repetitive, and within a one year period. "Alterations in the RBFOX1 gene have been found in various psychiatric and neurodevelopmental disorders that often are comorbid with anger, conduct disorders, and aggressive behaviors." (PMID 41009966, 2025).
cortical dysplasia (1 paper, 2015). "The results from western blot analysis revealed that the protein expression of RBFOX1 was markedly upregulated, not only in the patients with double cortex, but also in patients with focal cortical dysplasia and tuberous sclerosis." (PMID 25571999, 2015).
cryptorchidism (1 paper, 2018). The failure of one or both testes of a male fetus to descend from the abdomen into the scrotum during the late part of pregnancy. "Recently, we compared GWAS data from non-syndromic cryptorchidism cases vs. controls and from men with TGCT with or without a history of cryptorchidism vs. controls, and discovered suggestive signals in 19 genes, including RBFOX1 and RBFOX3, paralogs that encode RNA-binding proteins (RBPs)." (PMID 30083133, 2018).
Duchenne muscular dystrophy (1 paper, 2013). Duchenne muscular dystrophy (DMD) is a neuromuscular disease characterized by rapidly progressive muscle weakness and wasting due to degeneration of skeletal, smooth and cardiac muscle. "We also found that the level of Rbfox1 down-regulation parallels the severity of the disease in different muscles of FRG1 mice, while it is expressed at normal levels in the mouse model of Duchenne muscular dystrophy." (PMID 23300487, 2013).
genetic generalized epilepsy (1 paper, 2024). A generalized epilepsy that is understood to have a genetic etiology. "RBFOX1 regulates tissue-specific alternative splicing, has been associated with neurodevelopmental disorders and seizures, regulates the brain blood–tumor barrier, and is a germline risk locus for genetic generalized epilepsy." (PMID 39387520, 2024).
Hypercholesterolemia (1 paper, 2024). An increased concentration of cholesterol in the blood. "GS and Rbfox1 knockdown did not induce any change in current density, thus we speculated that reduced current densities in smooth muscle cells from HFD/STZ-induced diabetic rats may be attributed to other metabolic abnormalities, such as hypercholesterolemia or hyperinsulinemia." (PMID 38575795, 2024).
malaria (1 paper, 2016). Malaria is a serious and sometimes fatal disease caused by a parasite that commonly infects a certain type of mosquito which feeds on humans. "In addition to the genes in the cell-cell adhesion cadherin-catenin, and related pathways, two regulators of alternative splicing (RBFOX1 and SRPK2) in neurons and the vasculature showed very strong environmental correlations with malaria." (PMID 26744416, 2016).
malignant mesothelioma (1 paper, 2024). A malignant neoplasm of the pleura or peritoneum, arising from mesothelial cells. "In the study of Malignant Mesothelioma (MMt), a pure deletion mutation in RBFOX1/A2BP1 was also identified for the first time, and the possibility was raised that this gene could be deemed as a new suppressor in MMt20." (PMID 38167455, 2024).
mood disorder (1 paper, 2024). A cognitive disorder a disturbance in which the person's mood is hypothesized to be the main underlying feature. "RBFOX1 regulates the expression of large genetic networks during neurodevelopment and was one of the top genes identified in the largest GWAS of mood disorders." (PMID 38351009, 2024).
muscular atrophy (1 paper, 2023). The loss of muscle tissue due to inactivity or disease. "Interestingly, it has been demonstrated that overexpression of Mbnl or rbFox1 in Drosophila is capable of rescuing both muscular atrophy and the locomotion ability of flies bearing the CCUG repeat expansion." (PMID 37762484, 2023).
muscular dystrophy (1 paper, 2013). Muscular dystrophy (MD) refers to a group of more than 30 genetic diseases characterized by progressive weakness and degeneration of the skeletal muscles that control movement. "In addition, Rbfox1 was expressed at normal levels in mdx mice, indicating that its down-regulation in FRG1 mice is not generally associated with muscular dystrophy." (PMID 23300487, 2013).
myotonic dystrophy (1 paper, 2018). An inherited progressive disorder affecting the muscles. "In mouse models, knockout for rbFox1 or rbFox2 present severe skeletal muscle, heart and brain dysfunctions, which are different from the alterations observed in myotonic dystrophy." (PMID 29789616, 2018). "Hence, we tested whether the release of MBNL1 from CCUG RNA foci upon rbFOX1 overexpression may correct splicing alterations typical of myotonic dystrophy." (PMID 29789616, 2018).
myotonic dystrophy type 2 (1 paper, 2018). Myotonic dystrophy type 2 (MD2), also known as proximal myotonic myopathy, is a very rare genetic multi-system disorder of late childhood or adult-onset characterized by mild myotonia, muscle weakness, and rarely cardiac conduction disorders. "Overall, these data indicate that rbFOX1 and rbFOX2 are specific components of CCUG RNA foci in myotonic dystrophy type 2." (PMID 29789616, 2018).
Neurodegeneration (1 paper, 2023). Progressive loss of neural cells and tissue. "Interestingly, in advanced stages of cerebellar neurodegeneration, the expression of Rbfox1, Zfp521, and Chd7 host mRNAs was substantially decreased, in contrast to the surplus of the circRNA forms." (PMID 37019475, 2023).
nicotine dependence (1 paper, 2023). Physical and psychological dependence on nicotine. "RBFOX1 (also known as A2BP1) is highly expressed in neurons in brain regions that include the hippocampus, and there is evidence of associations between this gene, smoking cessation, and nicotine dependence." (PMID 37686494, 2023).
peripheral nerve injury (1 paper, 2024). Injury to a peripheral nerve. "Our results indicate that alternative RNA splicing of Nrcam exon 10 in DRG contributes to Rbfox1-mediated neuropathic pain resulting from peripheral nerve injuries." (PMID 38241164, 2024). "Consequently, Rbfox1-mediated RNA splicing can be a potential novel target intervention against pathological conditions, and restoring Rbfox1 abundance and function can be a new therapeutic approach for peripheral nerve injury-induced neuropathic pain." (PMID 38241164, 2024). "We identify NrCAM as a significant Rbfox1 target in injured DRGs after peripheral nerve injury." (PMID 38241164, 2024). "Notably, Rbfox1 expression is markedly reduced in injured DRG following peripheral nerve injury." (PMID 38241164, 2024).
pseudoexfoliation syndrome (1 paper, 2023). "Polymorphisms at RBFOX1 have been shown to be associated with pseudoexfoliation syndrome." (PMID 37351342, 2023).
Rett syndrome (1 paper, 2020). A severe neurodevelopmental disorder affecting the central nervous system. "Notably, RBFOX1 was also found to be differentially methylated in post-mortem brain of subjects with Rett syndrome and Dup15q syndrome, suggesting a fundamental role in neurodevelopment." (PMID 33054850, 2020).
substance dependence (1 paper, 2023). The psychological or physiological need to take a substance in order to experience its effects or to avoid the effects of its absence. "The RBFOX1 gene was identified as associated with substance dependence or the ability to quit smoking in 13 independent datasets, with smoking frequency." (PMID 37686494, 2023).
tauopathies (1 paper, 2019). "MiR-132 provides neuroprotection for tauopathies via regulating the tau modifiers acetyltransferase EP300, kinase GSK3β, RNA-binding protein Rbfox1 and proteases Calpain2 and Caspases 3/7." (PMID 30881384, 2019).
type 2 diabetes (1 paper, 2023). "Using forward 2SMR, we observed evidence of causality (adjusted p<0.001 or unadjusted p<0.05) between type 2 diabetes and lower levels of DNAm at the CpGs cg20812370 (PBX1) (p=0.002) and cg01577083 (RBFOX1) (p=0.023)." (PMID 37202507, 2023). "For associations at cg20812370 (PBX1) and cg01577083 (RBFOX1), there was little evidence of heterogeneity in the effect of 62 type 2 diabetes SNPs on DNAm levels based on the results of the Cochran’s Q test (Q range 52.9–74.8, p value range 0.10–0.75)." (PMID 37202507, 2023). "For comparison, CpGs that were likely to be secondary to the effects of type 2 diabetes (in PBX1, SPEG, MIR657 and RBFOX1) based on the results of the 2SMR analysis were enriched for perinatal and neurological traits in addition to cardiometabolic and anthropometric traits." (PMID 37202507, 2023).
vision disorder (1 paper, 2023). Any impairment to the vision. "Among the novel GWAS-identified associations with AL, our study revealed potential candidate genes, including SLC25A12, BMP3, RGR, RBFOX1, and MYO5B, which have all been linked to visual function or eye development and have been implicated in vision disorders." (PMID 37351342, 2023).
tumor (29 papers, 2012 to 2025). "Further accumulation of mutations in ZNF521, TRRAP, and RBFOX1 result in the metastatic clade that forms the third subclone (marked in red), and mark the point of tumor dissemination to the liver." (PMID 34149820, 2021). "We also checked the expression of U2AF2 and RBFOX1, two other known factors implicated in neuronal ME splicing, by semi-quantitative PCR between the three tumor grades." (PMID 33207694, 2020). "Among these rearrangements, 12 contained small exonal deletions, and most of the affected genes, including FHIT, CDH13, DACH1, and RBFOX1, have been reported as tumor suppressors or as deleted in cancer, suggesting their active role in tumorigenesis." (PMID 24937453, 2014). "Staining was detected in the cytoplasm of normal colonic epithelium and reduced levels of RBFOX1 expression were observed in the some of the tumour samples we tested." (PMID 23286373, 2013). "Novel RBFOX1 mutations were found in CRC cell lines and tumours; mRNA and protein expression was reduced in tumours." (PMID 23286373, 2013). "We next examined whether the expression of QKI and RBFOX1 also correlated with mesenchymal features in murine or human tumor samples." (PMID 30059005, 2018). "When a gain of 16p13.3 was present, the prognosis of these patients over all tumour stages was worse than the prognosis for patients without a 16p13.3 alteration or with a loss of the RBFOX1 gene (HR = 5.018, **P = 0.020)." (PMID 26222184, 2015). "Furthermore, in most tumour samples the expression level of RBFOX1 was reduced compared to the normal paired tissue samples." (PMID 23286373, 2013). "We note that the RBFOX family of proteins includes RBFOX1, RBFOX2, and RBFOX3; however, RBFOX1 and RBFOX3 show the greatest extent of downregulation across different tumours (>60-fold), whereas RBFOX2 shows comparatively moderate downregulation (~3-fold)." (PMID 35987939, 2022). "In glioblastoma, overexpression of RBFOX1 was found to increase the blood-tumor barrier permeability by increasing the stability of MAFF, which promoted doxorubicin delivery across the blood-tumor barrier, resulting in apoptosis of glioma cells." (PMID 33816259, 2021). "For the RBFOX1 gene, HBV integration events reduced the expression of RBFOX1 in the tumor-adjacent tissues comparing to the cancer tissue in two match pairs of samples." (PMID 23236287, 2012). "Notably, RBFOX1 is overexpressed in GBM, thereby playing a role in tumor viability by affecting the blood–brain barrier." (PMID 35887658, 2022). "We found that MACROD2, RBFOX1, and LRP1B were frequently affected by SVs in Chinese patients with HCC, suggesting that SVs in those genes might play a role in tumor development and progression." (PMID 32257385, 2020). "Furthermore, in the MNA tumours, RBFOX3 was upregulated, whereas RBFOX1 was downregulated, perhaps indicating changes in splicing." (PMID 32707690, 2020). "Therefore, we sought evidence of RBFOX1 expression by quantitative real time PCR (QRT-PCR) using cDNA from 43 colorectal cell lines and 19 paired CAU CRC tumour/normal tissues, where good quality RNA was available." (PMID 23286373, 2013).